IFNG (interferon gamma)
Diseases named in the same sentence as IFNG in open-access papers (continued):
Sharing a sentence is not in itself a finding about the gene and the disease.
viral infection (continued). "Transcriptomic and genomic studies have implicated alterations in key cytokines with SCZ, including increases in interferon regulatory factor 3 (IRF3), which is a major transcription factor in viral infection, and interferon gamma (IFN-γ), an important regulator of viral propagation." (PMID 33061891, 2020). "Indeed, this CD4+CD8+ T cell population exhibit properties of mature antigen-experienced memory/effector T cells, is characterized by the expression of IFNγ and plays a role in protection against viral infection." (PMID 31620134, 2019). "However, STAT1 represses whereas STAT4 activates IFNγ expression in T cells during a viral infection." (PMID 31228946, 2019). "Future research could focus on synergistic effects of IFNα and IFNγ or the use of recombinant chicken IFNs in vaccine formulations to boost the chicken immune system to ward off viral diseases." (PMID 31795203, 2019). "However, the role of IFNγ in viral infection remains contentious because IFNγ is known to promote a proinflammatory state in the brain." (PMID 31514273, 2019). "NK cells work to control viral infections by secreting IFNγ and TNFα." (PMID 31396204, 2019). "Mediators of viral infection (interferon-gamma) are thought to attenuate PCT levels." (PMID 30999808, 2019). "In viral infections, high concentration of interferon-gamma can suppress PCT production." (PMID 31821331, 2019). "Thus, we argue that IFNγ signaling has the potential to augment ASC development in settings, like autoimmunity and viral infection, where IFNγ and TLR ligands are present." (PMID 31090539, 2019). "Here, we show a novel role for IFNγ in regulating innate immune responses during a viral infection." (PMID 29352287, 2018). "Importantly, IFNγ emerges as a key regulator of the inflammatory response to virus infection and this functionality is distinct from its direct anti-microbial activities." (PMID 29352287, 2018). "Thus our data reveals a “division of labor” for IL-10 and IFNγ in the resolution of inflammation following viral infection, with IL-10 being important for control of IMs and IFNγ being essential for termination of neutrophil responses." (PMID 29352287, 2018). "While PD-1int CD8+ T cells elicited by acute LCMV-Armstrong viral infection remained functional (IFNγ) and downregulated PD-1 (to PD-1int) after the virus was cleared, PD-1hi-expressing CD8+ T cells displayed an exhausted phenotype in the face of chronic LCMV-clone-13 infection." (PMID 29483513, 2018). "Interleukin-12, together with interferon gamma, plays a vital role in fighting viral infections." (PMID 29304016, 2018). "Additionally, we investigated the effects of perforin and interferon-gamma (IFNγ) on the virus infection and found important roles for both mechanisms." (PMID 30153311, 2018). "Importantly, we were unable to detect any signatures of an adaptive immune response, such as antiviral cytokine IFNγ or cytolytic molecules perforin and granzyme B, needed to clear viral infection and establish memory." (PMID 29123522, 2017). "IRF1 is a known regulator of type I IFN expression and is responsive to IFNγ and viral infection." (PMID 27966453, 2017). "Since type I IFNs have been linked to BM aplasia and sensitize HSCs to cellular stress, it can be envisioned that initial IFNα/β exposure, as occurs in response to viral infection, may render HSCs more vulnerable to subsequent IFNγ-mediated impairment." (PMID 27621733, 2016). "The macrophage activation phenotype resulting from selective treatment with LPS, or in some cases a combination of LPS and interferon γ (IFNγ), is referred to as M(LPS) or M(LPS+IFNγ) activation, and is considered vital for the host response to bacterial or viral infection." (PMID 27462873, 2016). "One reason for keeping IFNγ up might be the need for an immediate defense against bacterial and viral infections." (PMID 27893767, 2016).
viral infection (continued). "Since IFNγ affected neural cell marker expression in the hippocampus and the whole brain (NSPC and neuron loss), we evaluated which IFN-signaling pathways are activated in the hippocampus during a viral infection." (PMID 27178303, 2016). "This is the first study to demonstrate that IFNγ protects NSPCs during a CNS viral infection." (PMID 27178303, 2016). "Genetic deficiencies in IFNγ signaling (and related pathways) are increasingly being identified; perhaps surprisingly, sufferers are not particularly susceptible to most viral infections, instead being vulnerable to infection by mycobacteria." (PMID 27580079, 2016). "From these results, we suspect that the anti-viral immune response is detrimental to NSPCs and that IFNγ may be protective against the detrimental effects of the immune response for NSPCs during a neonatal viral infection." (PMID 27178303, 2016). "This may be consistent with studies suggesting that antigen-activated CD8+ T lymphocytes can eliminate or control viral infection by secretion of IFNγ and TNFα [38, –40]." (PMID 27709126, 2016). "Taken together, our data show prominent induction of active immunoproteasomes in the lung by IFNγ in different alveolar cell types and by virus infection in vivo indicating that these cells are able to mount efficient immunoproteasome-mediated immune responses to infection." (PMID 25989070, 2015). "Furthermore, we also investigated the direct effect of viral infection and IFNγ resulted from virus-mediated Th1 immunity on the presentation of tumor-associated antigens (TAAs) to immune cells by the tumor cells." (PMID 24827739, 2014). "With an in vitro OVA modeling system, we offer the first and direct evidence that adenoviral infection and IFNγ resulted from in vivo viral infection increase the presentation of TAA to CD8+ T cells through the ‘classic’ endogenous pathway of MHC I presentation." (PMID 24827739, 2014). "In addition, viral infections are often accompanied by high serum interferon gamma levels, which inhibit the production of serum procalcitonin." (PMID 23843799, 2013). "Here we show for two acute virus infections and CD8+ T cells activated in vitro that DimerX (a tetramer variant) and intracellular staining for IFNγ, alone or in combination with CD107 to detect degranulation, gave comparable results at the peak of the response." (PMID 22745779, 2012). "Several studies have shown that the CD8 T-cells of children and infants of equivalent age to those whom we sampled have a weak IFNγ response to viral infections including CMV, making it unlikely that the IFNγ responses of the infants in the subcohort had peaked." (PMID 18682836, 2008). "However, the virus specific IFNγ responses were significantly lower than those observed in many other acute viral infections despite evidence of detectable virus in the blood." (PMID 19023425, 2008). "Thus, memory CD4+ T cells, like memory CD8+ T cells, elaborate IFNγ within hours of secondary viral infection." (PMID 18404208, 2008). "The antigen-specific mCD4+ T cells clustered in areas associated with interferon gamma (IFN-γ), tumor necrosis factor (TNF), and interleukin-2 (IL-2) expression, which are the signature cytokines of the type 1 T helper (TH1) cells typically induced during viral infections." (PMID 40124502, 2025). "Importantly, sex-related differences were evident: males showed greater weight loss and comparatively weaker cytokine responses in the brain and lung, whereas females mounted stronger pulmonary IFNγ responses, in agreement with higher immune responses observed in women during acute viral infections." (PMID 40895479, 2025). "However, we did not manage to validate any associations between the IFNγ NK cell responses and donor characteristics such as gender, age, seropositivity to viral infections (cytomegalovirus (CMV), SARS-CoV-2 and Epstein–Barr virus (EBV))." (PMID 38540262, 2024).
viral infection (continued). "However, IL-27 significantly augmented NKG2D activation of NK cells and subsequent IFNγ production, suggesting that IL-27 may act as an additional signal alongside IL-15 or IL-18 to enhance NK cell activation at the site of viral infection." (PMID 35634328, 2022). "Expression changes in UPS genes identified in both ST_EPN_RELA and PF_EPN_B included several differentially expressed UPS genes associated with interferon gamma signaling (MID1, PIAS1, TRIM2, TRIM22, TRIM45) that may promote a proinflammatory milieu similar to that observed upon viral infections." (PMID 36293188, 2022). "Furthermore, a PCT value of more than 0.5 ng/mL is considered as an indication of systemic bacterial or fungal infection.The viral infection leads to interferon-gamma production, which in turn leads to inhibition of procalcitonin production from various tissues." (PMID 36084093, 2022). "In addition, viral infection induced a general immmunostimulatory boost via the release of IFNγ." (PMID 36077380, 2022). "Furthermore, these 190 up-DEGs were significantly enriched in disease terms associated with viral infection and inflammation and 17 functional GO-terms (FDR < 0.05), including interferon alpha/beta signaling and interferon gamma signaling." (PMID 35172892, 2022). "The unresponsiveness of infant AMφs to IFNγ might be caused by their lack of exposure to viral infections, which have been shown to drive training and “innate macrophage memory” through CD8+ T cell-mediated priming of AMφs by IFNγ." (PMID 32265931, 2020). "Consequently, viral infection may disrupt the secretion of interferon, IFNG, INFGR1, and TNF genes upregulated in HPV-positive CRC tissues as compared to HPV-negative CRC tissues in this study." (PMID 32258125, 2020). "Additionally, NK cells can inhibit the spread of viral infections via their cytolytic action against infected cells and the production of proinflammatory cytokines and immune modulators such as interferon gamma (IFNγ) and the tumor necrosis factor alpha (TNFα)." (PMID 26296209, 2015). "Importantly, viral infection and IFNγ increased the presentation of OVA antigen in OVA-expressing cells to CD8+ T-cell hybridoma B3Z cells, which is blocked by brefeldin A and proteasome inhibitors, indicating the activity is through the biosynthesis and proteasome pathway." (PMID 24827739, 2014). "The up-regulation via viruses and the effects of the inflammatory cytokine IFNγ imply a more general role for CEACAM1 and CEACAM5 in the inflammatory response to infection, and also in the spatial and temporal association between bacterial and viral infections." (PMID 23941132, 2013). "While in most situations, namely viral infections, this class of cytokines is indispensable for host survival they mediate a detrimental effect during infection with L. monocytogenes by rendering macrophages insensitive towards IFNγ signalling which leads to a lethal bacterial pathology in mice." (PMID 21179567, 2010). "Moreover, the absence of IFNγ in deficient mice induced the death of hippocampal CA1 neurons after virus infection, suggesting a neuroprotective role of IFNγ in the brain." (PMID 21073708, 2010). "This shift allows them to sustain the production of pro-inflammatory cytokines such as interferon-gamma (IFNγ), tumor necrosis factor (TNF), and interleukin-2 (IL-2), which drive immune responses against viral infections." (PMID 40453076, 2025). "Our stimulation panel included stimuli that trigger pro- and anti-inflammatory pathways in macrophages (IFNβ, IFNγ, interleukin-4/IL4) and those that induce response to viral infection (Resiquimod/R848, Poly I:C/PIC)." (PMID 40866338, 2025). "As expected, viral infection led to a marked upregulation of inflammatory cytokines, such as IL6, IL8, IL1B1, and IFNG, together with TGFB, indicating a strong immunomodulation to infection." (PMID 41157575, 2025).
viral infection (continued). "Given the critical role of T-cell immunity in defending against viral infections, the secretion of MPXV-specific interferon-gamma (IFN-γ) lymphocytes in the spleen was detected using enzyme-linked immunospot (ELISpot) on Day 42 after primary immunization." (PMID 40105863, 2025). "Overexpression of JAK1, TYK2, MAP2K1, IFNG, TRPM2, and ADCY9 significantly inhibited viral infection, whereas overexpression of SNX27, GATA4, EHMT2, PCBP2, SMARCA4, and SLX4 enhanced viral infection." (PMID 40530850, 2025). "To illustrate, the viral infection results in CD8+ T-lymphocytosis, releasing a pool of cytokines, including interferon-gamma, interleukin-2, and TNF-alpha." (PMID 38883093, 2024). "IFNγ can be secreted by innate lymphocyte cells, γδ T cells, and CD4+ and CD8+ T cells during viral infections." (PMID 38510965, 2024). "The control of viral infection in NIFs is mediated primarily by CD4 and CD8 T cells in an IFNγ-dependent manner." (PMID 39134803, 2024). "Viral infections in mice indicate a role for DLL1 ligand response and IFNγ increase in countering these viral infections." (PMID 38542260, 2024). "In response to viral infection, CD4+ T cells primarily differentiate into Th1 cells and secrete significant quantities of IFNγ." (PMID 38770891, 2024). "Regarding the control of chronic viral infections such as persistent measles virus infection of the brain, pharmacologically blocking Ac activity or genetic approaches to knock out Ac expression in T cells might enhance viral clearance through enhanced IFNγ secretion." (PMID 38919612, 2024). "IFNγ-producing T cells, i.e., CD4+ Th1 and CD8+ cytotoxic T lymphocytes, are crucial in viral infections." (PMID 37371616, 2023). "Although individuals with DS do not present markedly elevated levels of circulating IFNs as seen in other interferonopathies or during viral infections, the IFN transcriptional response is nonetheless elevated, tracking preferentially with IFNG levels." (PMID 37379383, 2023). "During an immune response, NK cells produce chemokines, as well as cytokines, including interferon-gamma (IFN-γ) and tumor necrosis factor-alpha (TNF-α), which are important for host protection against viral infection and tumor formation." (PMID 37445721, 2023). "IFNγ stimulates type I IFN production and orchestrates the immune response to viral infection, promotes antiviral activity via NK cells, and enhances antigen presentation and phagocytosis of MΦ." (PMID 38006022, 2023). "IL-25 promoted the infection of HSV-1 among AD patients by suppressing the expression of interferon-gamma (IFN-γ), a key factor for the host to defend against viral infection." (PMID 36119076, 2022). "Liu, Zhang52 reported that NF-kB was activated by several stimuli including TNF-α, interferon-gamma (IFN-γ), interleukins, bacterial and viral infection." (PMID 35654991, 2022). "SARS-CoV-2-specific CD4+ Th1 cells that produce IFNγ, TNF-ɑ, and/or IL-2 can be detected in vaccinators or convalescents, which is similar to other viral infections." (PMID 36032096, 2022). "An exception is interferon-gamma (IFN-γ) which reduces PCT expression, therefore resulting in the lower concentrations of PCT found in viral infections." (PMID 34079538, 2021). "Interferon gamma (IFNγ) is predominantly produced by TH1, TC1, and NK cells during viral infections." (PMID 33725263, 2021). "Interferon-gamma (IFN-g) is an important cytokine for innate and adaptive immunity to viral infections and activator of macrophages." (PMID 34068196, 2021). "Antigen-specific immunity drives the production of interferon gamma (IFNγ; a type II interferon) by CD8+ cytotoxic T lymphocytes (CTLs), which helps to control virus infection and cancer." (PMID 32194559, 2020). "In response to viral infection, CD226 KO mice showed delayed lymphocytic choriomeningitis virus (LCMV) clearance, with reduced IFNγ and TNFα production by virus-specific CD8+ T cells." (PMID 33013915, 2020).
viral infection (continued). "bulgaricus OLL1073R-1 induced interferon gamma (IFN-γ) production and activated natural killer (NK) cells in mice, which contributed to anti-viral infection effect." (PMID 33195367, 2020). "Clearance of viral infections, however, requires additional immune response including type II IFN, i.e., IFNγ, which is produced by activated CD8+ T cells." (PMID 30704498, 2019). "Inhibitors of IL8 and targeting IL12, IL2, interferon-gamma (IFNγ) and tumor necrosis factor-α (TNF-α) are other possible immune-modulators used to combat some viral infections." (PMID 31787892, 2019). "The increased expression of endothelial MHC molecules can be induced by interferon gamma (IFN-γ), a cytokine that is released commonly during virus infections." (PMID 29536322, 2018). "In this regard, the type 1 helper T cell pathway of response, signaled by increased production of interferon gamma (IFN-γ) and inflammation, is critical to activation of cytotoxic T cells for clearance of the peripheral virus infection." (PMID 30270888, 2017). "Notably, IFNγ was shown to directly reduce HSC self-renewal during recovery from viral infection where robust type I IFNs had ablated the HSC pool, suggesting that type I IFNs may potentiate the suppressive impact of IFNγ on hematopoiesis during viral infection." (PMID 27621733, 2016). "We and others have previously reported the transient burst of IFNγ by CD8+ T cells in response to homologous and heterologous secondary viral infection; the focus of the present study was on T1IFN." (PMID 27580079, 2016). "Interferon-gamma (IFN-γ), an important mediator in viral infections, down-regulates PCT production, making PCT a very useful test to help distinguish between viral and bacterial infections." (PMID 28702296, 2016). "Thus, blocking or failure of the IFNγ signaling pathway confers higher susceptibility to infections, suggesting that secretion of IFNγ may be an important effector function for the suppression of HIV-1 and other viral infections." (PMID 25802474, 2015). "Finally and most importantly, we show that interferon gamma given 24 hours prior to or after virus infection protects mice from lethal Ebola virus challenge, suggesting that this drug may serve as an effective prophylactic and/or therapeutic strategy against this deadly virus." (PMID 26562011, 2015). "CD8+ cytotoxic T cells secreting interferon-gamma (IFN-γ) or/and tumor necrosis factor alpha (TNF-α) are important components in mediating host immunity against viral infections and have been shown to play critical roles in BKV clearance." (PMID 23251224, 2012). "To elucidate the contribution of the virus infection to the macrophage activation, we infected the macrophages at a MOI of 1 with ΔM36, M36rev or mock-infected them in the presence of Zymosan and IFNγ." (PMID 23271968, 2012). "It is highly likely that the larger concentrations of IFNγ, MIP-1β and RANTES were due to their central role in controlling viral infections as they have previously been shown to potently inhibit HIV infection." (PMID 21655330, 2011). "In this viral infection, CD8 clones are initially generated, but cytotoxicity and proliferation are lost at an early stage, while IFNγ persists for a longer period." (PMID 21072232, 2010). "The activation of mononuclear system cells occurs due to a hypersecretion of proinflammatory cytokines (IFNγ, TNFα, IL6, IL10, M-CSF), as a consequence of a triggering agent, which is often a viral infection." (PMID 18834507, 2008). "The activation of the interferon gamma response pathway is expected in response to cancer antigens rather than interferon alpha response upon viral infection." (PMID 40032842, 2025). "The observed upregulation in IFNG within these six non-lymphoid tissues was entirely restricted to highly infected fetuses, further supporting local viral infection." (PMID 38389522, 2024).